RNA5S14 (RNA, 5S ribosomal 14)
Synonyms: RN5S14
Gene: Ribosomal RNA gene on chromosome 1 (228,639,337 to 228,639,455, reverse strand). Ensembl gene ENSG00000201355.
Gene Ontology:
Molecular function: structural constituent of ribosome
Cellular component: ribosome
Homologues: Orthologues: dog 5S_rRNA (100% identical), macaque 5S_rRNA (97% identical). Paralogues in human: RNA5S1 (100% identical), RNA5S10 (100% identical), RNA5S11 (100% identical), RNA5S12 (100% identical), RNA5S13 (100% identical), RNA5S15 (100% identical), RNA5S16 (100% identical), RNA5S17 (100% identical), RNA5S2 (100% identical), RNA5S3 (100% identical), RNA5S4 (100% identical), RNA5S5 (100% identical), and 26 more.